FITM1 (fat storage inducing transmembrane protein 1)
Description:
Plays an important role in the formation of lipid droplets (LDs) which are storage organelles at the center of lipid and energy homeostasis (By similarity). Directly binds to diacylglycerol (DAGs) and triacylglycerol (By similarity).
Synonyms: FIT1
Tractability: Antibody: UniProt predicts a signal peptide or a membrane-spanning region.
Gene: Protein-coding gene on chromosome 14 (24,130,659 to 24,132,849, forward strand). Ensembl gene ENSG00000139914.
Subcellular location: Endoplasmic reticulum membrane
Pathways (Reactome):
Metabolism: Lipid particle organization
Gene Ontology:
Molecular function: diacylglycerol binding; endoplasmic reticulum-lipid droplet tether activity; triglyceride binding; coenzyme A diphosphatase activity
Biological process: fat cell differentiation; lipid droplet formation; lipid droplet organization; lipid storage; phospholipid biosynthetic process
Cellular component: endoplasmic reticulum membrane
Genetic constraint (gnomAD): Loss-of-function variants: 11 observed, 22.34 expected, observed/expected ratio (o/e) 0.49, 90% interval 0.31 to 0.81. The upper end of that interval is the gene's LOEUF score, 0.81, which puts it in group 3 of 6, group 1 being the genes least tolerant of losing a copy. Missense variants: 394 observed, 394.42 expected, observed/expected ratio (o/e) 1, 90% interval 0.92 to 1.09. Synonymous variants: 164 observed, 175.96 expected, observed/expected ratio (o/e) 0.93, 90% interval 0.82 to 1.06.
Homologues: Orthologues: macaque FITM1 (99% identical), dog FITM1 (99% identical), chimpanzee FITM1 (98% identical), guinea pig FITM1 (98% identical), pig FITM1 (98% identical), rabbit FITM1 (97% identical), mouse Fitm1 (96% identical), rat Fitm1 (96% identical), tropical clawed frog fitm1 (50% identical), zebrafish fitm1l (38% identical), Drosophila melanogaster Fitm (26% identical), Caenorhabditis elegans fitm-2 (18% identical). Paralogues in human: FITM2 (27% identical).
Diseases named in the same sentence as FITM1 in open-access papers:
FITM1 is named in the same sentence as 15 diseases in open-access papers, as found by Europe PMC text mining. Sharing a sentence is not in itself a finding about the gene and the disease. The quoted sentences say what the papers report.
chronic heart failure (1 paper, 2019). "The mRNA expression of Fitm1 and Fitm2 was decreased in heart failure model mice, and Fitm2 hetero-knockout [Fitm2 (+/−)] mice exhibited resistant profiles to pressure-induced chronic heart failure." (PMID 30923760, 2019).
heart failure (1 paper, 2019). Inability of the heart to pump blood at an adequate rate to meet tissue metabolic requirements. "Neither constitutive Fitm1 (−/−) aged nor heart failure model mice showed significant differences in heart size or function." (PMID 30923760, 2019). "Therefore, we here report the profiles of FITM1 and FITM2 in mouse models of heart failure." (PMID 30923760, 2019).
pancreatic cancer (1 paper, 2021). "Among 39 differentially expressed factors, seven up-regulated genes (CAV2, CIDEC, HILPDA, HSD17B11, NCEH1, RAB5A, and SQLE) and two down-regulation genes (BSCL2 and FITM1) were significantly associated with overall survival of pancreatic cancer patients." (PMID 34078402, 2021). "We further identified that enhanced expression of 7 genes namely CAV2, CIDEC, HILPDA, HSD17B11, NCEH1, RAB5A, and SQLE are associated with significantly shorter overall survival whereas elevated expression of BSCL2 and FITM1 correlates with longer overall survival of pancreatic cancer patients." (PMID 34078402, 2021).
cancer (2 papers, 2020 to 2023). A tumor composed of atypical neoplastic, often pleomorphic cells that invade other tissues. "We figured out that low FITM1 expression could activate cancer-related pathway." (PMID 32174969, 2020). "Based on the investigation of 101 non-viral HCC patients in TCGA, we demonstrate that the hypermethylated FITM1 down-regulates the corresponding FITM1 expression, thereby promoting the progression of non-viral HCC via cancer-related pathways." (PMID 32174969, 2020).
metabolic disorders (1 paper, 2020). "As for FITM1, previous study showed that knocking out the FITM1, the lipid droplet accumulation reduces, suggesting that the expression of FITM1 has a connection with lipid droplet, which has a great impact on inflammation, metabolic disorders, and cell injury in liver." (PMID 32174969, 2020).
tumor (1 paper, 2020). "In our study, we revealed that FITM1 expression was much lower in tumor tissues compared with other seven key genes or corresponding normal samples." (PMID 32174969, 2020). "Moreover, the FITM1 methylation was highly up-regulated in tumor specimens (Log FC = 0.49, P-value = 2.00E-09)." (PMID 32174969, 2020). "However, only FITM1 expression was significantly down-regulated in tumor specimens (Log FC = -1.74, P-value = 8.75E-09) while other three were over-expressed." (PMID 32174969, 2020). "Significantly, only 1 methylation curve of FITM1 or GPAM was gathered, indicating that the hypermethylated status of FITM1 and GPAM were centralized and common in tumor samples." (PMID 32174969, 2020). "This significantly negative correlation between methylation and expression in tumor as well as normal tissues triggered us to further explore the specific function of FITM1." (PMID 32174969, 2020). "Low expression of FITM1, ABCG5, BSCL2, and GPAM in non-viral HCC tumor specimens generally predicted worse survival status." (PMID 32174969, 2020).
FITM1 also shares sentences with these, for which no sentence is quoted: breast carcinoma (1 paper); Huntington disease (1); neurodegenerative disease (1); non-small cell lung carcinoma (1); ovarian carcinoma (1); pancreatic ductal adenocarcinoma (1); Parkinson disease (1); steatosis (1); viral infection (1).